ACTN3 (actinin alpha 3)
Description:
F-actin cross-linking protein which is thought to anchor actin to a variety of intracellular structures. This is a bundling protein.
Synonyms: ACTN3D
Tractability: Antibody: its Gene Ontology location is reachable by antibodies, with medium confidence. PROTAC: ubiquitination databases record sites on it.
Gene: Protein-coding gene on chromosome 11 (66,546,395 to 66,563,334, forward strand). Ensembl gene ENSG00000248746.
Subcellular location (Human Protein Atlas): Actin filaments; Focal adhesion sites; Cytosol; Primary cilium; Primary cilium transition zone
Pathways (Reactome):
Cell-Cell communication: Nephrin family interactions
Muscle contraction: Striated Muscle Contraction
Gene Ontology:
Molecular function: identical protein binding; protein binding; transmembrane transporter binding; actin filament binding; integrin binding; structural constituent of muscle; calcium ion binding
Biological process: focal adhesion assembly; actin cytoskeleton organization; muscle cell development; negative regulation of calcineurin-NFAT signaling cascade; negative regulation of cold-induced thermogenesis; negative regulation of glycolytic process; negative regulation of oxidative phosphorylation; positive regulation of glucose catabolic process to lactate via pyruvate; positive regulation of skeletal muscle tissue growth; regulation of aerobic respiration; regulation of apoptotic process; regulation of the force of skeletal muscle contraction; response to denervation involved in regulation of muscle adaptation; skeletal muscle atrophy; transition between fast and slow fiber; bone morphogenesis; negative regulation of relaxation of muscle; positive regulation of bone mineralization involved in bone maturation; positive regulation of fast-twitch skeletal muscle fiber contraction; positive regulation of skeletal muscle fiber development; regulation of muscle system process
Cellular component: extracellular exosome; focal adhesion; actin filament; cell junction; cortical actin cytoskeleton; cytosol; plasma membrane; pseudopodium; Z disc; actin cytoskeleton; brush border; cytoplasm; sarcomere
Genetic constraint (gnomAD): Loss-of-function variants: 91 observed, 114.75 expected, observed/expected ratio (o/e) 0.79, 90% interval 0.67 to 0.94. The upper end of that interval is the gene's LOEUF score, 0.94, which puts it in group 4 of 6, group 1 being the genes least tolerant of losing a copy. Missense variants: 1,221 observed, 1,189.1 expected, observed/expected ratio (o/e) 1.03, 90% interval 0.98 to 1.08. Synonymous variants: 456 observed, 461.65 expected, observed/expected ratio (o/e) 0.99, 90% interval 0.91 to 1.07.
Homologues: Orthologues: mouse Actn3 (97% identical), rabbit ACTN3 (97% identical), rat Actn3 (97% identical), pig ACTN3 (97% identical), dog ACTN3 (97% identical), chimpanzee ACTN3 (95% identical), guinea pig ACTN3 (95% identical), macaque ACTN3 (94% identical), tropical clawed frog actn3 (84% identical), zebrafish actn3b (83% identical), zebrafish actn3a (82% identical), Caenorhabditis elegans atn-1 (61% identical). Paralogues in human: ACTN2 (79% identical), ACTN1 (77% identical), ACTN4 (73% identical), SPTBN2 (31% identical), SPTBN1 (31% identical), SPTBN4 (30% identical), SPTB (29% identical), PLEC (27% identical), SPTBN5 (27% identical), MACF1 (26% identical), DST (26% identical), SYNE1 (25% identical), and 24 more.
Diseases named in the same sentence as ACTN3 in open-access papers:
ACTN3 is named in the same sentence as 62 diseases in open-access papers, as found by Europe PMC text mining. Sharing a sentence is not in itself a finding about the gene and the disease. The quoted sentences say what the papers report.
sarcopenia (21 papers, 2014 to 2025). Progressive decline in muscle mass due to aging which results in decreased functional capacity of muscles. "Lastly, certain polymorphisms of Alpha-actinin-3 (ACTN3) were shown to genetically predispose to post-transplant sarcopenia." (PMID 41464844, 2025). "A number of studies have been conducted in order to examine the association between ACTN3 genotypes and the risk of developing sarcopenia." (PMID 40869996, 2025). "We also identified that within the 253 obese elderly women, there were three SNPs that were associated with sarcopenia, namely, ACTN3 rs1815739, MTHFR rs1801131, and MTHFR rs1537516." (PMID 34768452, 2021). "Some studies have shown an association between the ACTN3 genotype and sarcopenia-related declines in muscle phenotypes in older adults." (PMID 34501725, 2021). "The present study identified elderly women with obesity who were ACTN3 rs1815739 RR homozygotes to be at a nearly-2-fold higher risk of sarcopenia than X-allele carriers." (PMID 34768452, 2021). "Under the adjusted recessive model, the ACTN3 X homozygotes showed a more than twofold increased risk of sarcopenia with increasing age." (PMID 33505434, 2020). "The study provides evidence that the genotypes of MTHFR, NRF2, and ACTN3 genes are associated with sarcopenia risk in older Caucasian adults." (PMID 33505434, 2020). "For the recessive model, the contribution of the MTHFR gene to sarcopenia risk was 22%, the ACTN3 gene 3.7%, and the NRF2 gene 4.3%, respectively." (PMID 33505434, 2020). "The ACTN3 R577X genotype exhibits a potential modifying effect on muscle deterioration (sarcopenia), which is associated with aging." (PMID 31145768, 2019). "This ability to more effectively maintain fast-twitch fiber size and mass with age is perhaps the mechanism by which ACTN3 genotype modifies the age-related loss in muscle function, and concurrent increased fall and sarcopenia risk." (PMID 29416549, 2018). "In summary, we examined the association between the ACTN3 R577X polymorphism and sarcopenia and osteoporotic status in older Korean adults and found increased risk for sarcopenia and osteoporosis with the X allele." (PMID 28626757, 2017). "Few studies have investigated the association of ACTN3 genotypes with sarcopenia and osteoporotic status in Asian populations." (PMID 28626757, 2017). "This study investigated the association of the ACTN3 polymorphism with sarcopenia and osteoporotic status in older Korean adults." (PMID 28626757, 2017). "This study investigated the association between ACTN3 genotype and susceptibility to sarcopenia and osteoporotic status in older Korean adults." (PMID 28626757, 2017). "In this study, therefore, we examined the susceptibility of ACTN3 R577X genotype to sarcopenia and osteoporotic status in a sample of Korean older adults and found the detrimental influence of the X allele on LBM and BMD." (PMID 28626757, 2017). "Limited data suggest that ACTN3 polymorphisms may be associated with post-transplant muscle loss, indicating a genetic predisposition to sarcopenia." (PMID 41464844, 2025). "It will therefore be helpful to determine whether the association between MTHFR, NRF2, ACTN3 genes, and sarcopenia is sex-specific." (PMID 33505434, 2020). "From a muscle phenotype perspective, an association between ACTN3 genotype and sarcopenia seems logical; specific type-II muscle fiber atrophy is a hallmark of sarcopenia, and, in athletic populations at least, the R allele is associated with an increase in type-II muscle fibers." (PMID 29416549, 2018). "In this paper, we have examined the potential influence of ACTN3 on three conditions associated with poorer outcomes with aging; sarcopenia and the resulting loss of muscle function, a loss of BMD, and a potential increase in metabolic disturbances, such as insulin resistance." (PMID 29416549, 2018).
sarcopenia (continued). "In particular, the R allele of ACTN3 tends to be associated with better maintenance of muscle mass, strength and function, a greater adaptive response to training, and is protective against the development of sarcopenia." (PMID 29416549, 2018). "The general consensus from these studies is that ACTN3 genotype exhibits a potentially modifying effect on muscle mass, maintenance of muscle function, and sarcopenia risk in elderly subjects, with the R allele associated with greater maintenance of strength and function, and sarcopenia protection." (PMID 29416549, 2018). "However, the current study extends the previous finding by reporting that the ACTN3 genotype is significantly associated with variability of osteoporotic status as well as sarcopenia in a relatively large sample size of Korean older adults." (PMID 28626757, 2017). "Collectively, these previous findings suggest that the ACTN3 gene X allele may share common pathways mediating susceptibility to sarcopenia and osteoporosis associated with aging." (PMID 28626757, 2017). "Third, lifestyle risk factors such as physical inactivity, poor fitness, and malnutrition may be significant modulators in determining the susceptibility of people with the ACTN3 genotype to sarcopenia and osteoporosis." (PMID 28626757, 2017). "Previous studies have shown that the ACTN3 genotype is a modulator of muscle mass and function and of sarcopenia risk in elderly adults, initially being the allele R of ACTN3 R577X associated with greater maintenance of strength and function or with sarcopenia protection." (PMID 33504021, 2021). "Due to a larger proportion of women, the associations between the ACTN3 R577X genotype and metabolic properties of the skeletal muscle may be more pronounced in our population and contribute to the positive association of 577X allele with the sarcopenia." (PMID 33505434, 2020). "Nevertheless, given that loss of muscle mass increases risk of insulin resistance, a precursor to type-II diabetes, and that type-II diabetes itself increases the risk of sarcopenia, it appears that ACTN3 genotype may modify type-II diabetes risk in the elderly." (PMID 29416549, 2018). "Therefore, whether gender modulates the association between the ACTN3 genotype and sarcopenia and osteoporosis remains to be determined." (PMID 28626757, 2017). "Second, the ACTN3 R577X polymorphism and its association with sarcopenia may be gender-dependent." (PMID 28626757, 2017). "Previous studies have associated polymorphisms with sarcopenia (ACTN3; MTHFR; NRF2), muscle hypertrophy (TGFβ; Myostatin, GDF-8) and response to ST (ACTN3, ACE, NOS3, PPARGC1A/B, VEGFA)." (PMID 40648598, 2025). "Recent studies have indicated a potential correlation between the development of sarcopenia and specific genetic polymorphisms in the methylenetetrahydrofolate reductase (MTHFR), alpha-actinin-3 (ACTN3), and nuclear respiratory factor 2 (NRF2) genes." (PMID 40869996, 2025). "Studies to date have explored the relationship between Single Nucleotide Polymorphisms (SNPs) and sarcopenia, focusing on vitamin D receptor (VDR), interleukin-6 (IL6), alpha-actinin-3 (ACTN3), and Myostatin (MSTN) polymorphisms." (PMID 40772803, 2025). "Among them, ACTN3 (actinin alpha 3) is a structural component of the sarcomeric Z line and is related to sarcopenia and physical fitness inactive older women." (PMID 36457054, 2022). "Sarcopenia was reported to be associated with methylenetetrahydrofolate reductase (MTHFR), alpha-actinin-3 (ACTN3), and nuclear respiratory factor 2 (NRF2) genotypes." (PMID 34943268, 2021). "Adjusted for age and height, three SNPs (ACTN3 rs1815739, MTHFR rs1801131, and MTHFR rs1537516) were associated with sarcopenia in obese participants." (PMID 34768452, 2021). "To date, five studies have investigated the association of SNPs with sarcopenia; limited to VDR, IL6, ACTN3 and MSTN polymorphisms." (PMID 32076017, 2020).
sarcopenia (continued). "As shown in this study, the contribution of a single gene polymorphism ranged from 3.7 to 5%, while the combined effect of all three polymorphisms (MTHFR C, ACTN3 X, and NRF2 C) explained as much as 39% of the interindividual variability in sarcopenia risk." (PMID 33505434, 2020). "The combined effect of MTHFR C, ACTN3 X and NRF2 C alleles is likely to be detrimental to older adults, with three or more of these alleles increasing the likelihood of sarcopenia." (PMID 33505434, 2020). "Sarcopenia was associated with the genotype distribution of the MTHFR in rs1801131 (p < 0.001), ACTN3 in rs1815739 (p = 0.043), and NRF2 in rs12594956 (p = 0.015) polymorphisms." (PMID 33505434, 2020). "Our study has shown an association between polymorphisms in the genes MTHFR, ACTN3, and NRF2 and sarcopenia." (PMID 33505434, 2020). "This study analyzed 24 SNPs but found that only ACTN3 rs1815739, MTHFR rs1801131, and MTHFR rs1537516 were found to be significantly associated with sarcopenia in obese women, highlighting an increased risk of developing this condition based on genetic profile." (PMID 40428823, 2025). "However, the current evidence regarding the role of ACTN3 rs1815739 in sarcopenia and sarcopenic obesity remains preliminary, limited by modest effect sizes, methodological constraints, and an insufficient mechanistic understanding." (PMID 40428823, 2025). "The discordant outcomes of this study imply that factors such as ethnicity, gender, physical activity level, and potentially other genetic modifiers may influence the relationship between ACTN3 genotype and sarcopenia." (PMID 40869996, 2025). "Three gene variants (ACTN3 rs1815739, MTHFR rs1801131, and MTHFR rs1537516) suspected to affect muscle function, homocysteine metabolism, or DNA methylation, respectively, were associated with sarcopenia in obese elderly women." (PMID 34768452, 2021). "Three gene variants (ACTN3 rs1815739, MTHFR rs1801131, and MTHFR rs1537516) previously reported to affect muscle function, homocysteine metabolism, or suspected to affect DNA methylation, were associated with sarcopenia in obese elderly women." (PMID 34768452, 2021). "It should be noted that the SNPs showing associations in the present study (ACTN3 rs1815739, MTHFR rs1801131, and MTHFR rs1537516) are different from our previous study that identified associations of FTO, TRHR, ESR1, and NOS3 gene variants with sarcopenia." (PMID 34768452, 2021). "Therefore, we focused on the determination of the single and combined effect of MTHFR, ACTN3, NRF2, VDR FokI, ADRB2, and NPAS4 polymorphism associated with sarcopenia in older adults." (PMID 33505434, 2020). "Despite the strong association with sarcopenia, no single muscle characteristic was associated with the ACTN3 polymorphism, except for non-significant differences in grip strength for ACTN3 XX homozygotes in men." (PMID 33505434, 2020). "Given the importance of resistance training in preventing and treating sarcopenia, the ACTN3 R577X genotype could modify resistance training adaptations." (PMID 31145768, 2019). "Given that resistance training is an important tool in sarcopenia prevention and treatment, and that ACTN3 genotype may modify resistance training adaptations, it is important to explore whether such a relationship exists in an elderly population." (PMID 29416549, 2018). "The contrasting allelic associations of ACTN3 rs1815739 and MTHFR rs1801131 observed between obese elderly women and the general elderly population underscore the multifactorial nature of sarcopenia and sarcopenic obesity, highlighting the necessity of context-specific genetic profiling." (PMID 40428823, 2025). "Besides ACTN3, NRF2 polymorphism is also associated with sarcopenia risks among elderly." (PMID 37493006, 2023). "First, a cause-effect relationship of the ACTN3 genotype and sarcopenia and osteoporosis could not be determined due to the cross-sectional nature of the study." (PMID 28626757, 2017).
sarcopenia (continued). "Under the dominant model, the contribution to the interindividual variability in sarcopenia trait was 4.8% for the MTHFR gene, 5% for the ACTN3 gene, and 4.4% for the NRF2 gene." (PMID 33505434, 2020). "With respect to sarcopenia, there was a significant difference (p = 0.016) in ASM index across ACTN3 genotypes." (PMID 28626757, 2017). "These revealed an association between ACTN3 and VDR gene variants and sarcopenia, while no such association was observed for IL6 variants and a specific MSTN variant linked to strength in athletes." (PMID 40772803, 2025). "On the other hand, genetic factors reported as sarcopenia biomarkers have also been identified such as angiotensin I-converting enzyme I (ACE), myostatin (MSTN), alpha actinin 3 (ACTN3), ciliary neurotrophic factor (CNTF), vitamin D receptor (VDR), insulin-like growth factor 1 (IGF1), and IL-6." (PMID 39194921, 2024). "Odds ratio (OR) and 95% confidence interval of MTHFR, ACTN3, and NRF2 genotypes for sarcopenia." (PMID 33505434, 2020).
Obesity (10 papers, 2015 to 2025). Accumulation of substantial excess body fat. "The study investigating the association between α-actinin-3 deficiency and obesity in both mice and humans showed mixed results regarding the role of ACTN3 R577X in weight gain and obesity among individuals of European descent." (PMID 39085321, 2024). "Human association studies exploring the effect of ACTN3 genotype on body mass and obesity have provided mixed results." (PMID 28293018, 2017). "Therefore, findings from our study such as the lower BMI of the male XX carriers, together with the simultaneous low prevalence of XX homozygotes and high number of overweight and obese participants support an association between the ACTN3 genotype and obesity." (PMID 34501725, 2021). "In conclusion, the prevalence of the ACTN3 577XX genotype is higher in T2D patients, but the genotype distribution is unrelated to metabolic control or obesity." (PMID 25780092, 2015). "Although the prevalence of the ACTN3 577XX genotype was higher in T2D patients, genotype distribution was unrelated to metabolic control or obesity." (PMID 25780092, 2015). "Among those genes, the ACTN3 (Actinin alpha 3) constitutes an interesting candidate to regulate muscle performance through the calcineurin signalling and the DHCR7 gene (7-dehydrocholesterol reductase) associated with obesity through vitamin D pathway." (PMID 29522525, 2018). "In addition, six independent human cohorts were genotyped for ACTN3 R577X (Rs1815739) and body mass index (BMI), waist-to-hip ratio-adjusted BMI (WHRadjBMI) and obesity-related traits were assessed." (PMID 28293018, 2017). "The X-allele has undergone strong positive selection during recent human evolution, and in this study, we sought to determine whether ACTN3 genotype influences weight gain and obesity in mice and humans." (PMID 28293018, 2017). "In addition, we were able to determine correlations between individual miRNAs, miR-20a-5p, −22-5p, and −101-3p (p < 0.04), and the genetic predisposition for endurance and/or strength and obesity risk (ACE, ACTN3, and FTO), as well as between miRNAs and the body composition (p < 0.05)." (PMID 35937778, 2022). "While the Actn3 KO 129X1/SvJ mice gained less weight compared to the wild-type (WT) mice when fed a high-fat diet (HFD) comprising 45% of calories from fat, the study found no significant contribution of the ACTN3 genotype alone to BMI or obesity in humans across six independent cohorts." (PMID 39085321, 2024). "In humans, ACTN3 genotype alone does not contribute to alterations in BMI or obesity." (PMID 28293018, 2017).
Hypertension (4 papers, 2014 to 2024). The presence of chronic increased pressure in the systemic arterial system. "In conclusion, in our study the XX genotype of the ACTN3 R577X polymorphism is associated to higher triglycerides and fasting glucose concentrations in women with diabetes and hypertension." (PMID 37948561, 2023). "Based on these evidences, the present study aimed to analyze the associations between I/C ACE, R577X ACTN3 and T(-107)C PON1 polymorphisms and metabolic and anthropometric parameters in women with diabetes and hypertension." (PMID 37948561, 2023). "The external replication of the study is limited, in particular for variants that were not previously reported to be associated with diabetes and hypertension, like ACTN3." (PMID 37948561, 2023).